GFAP (glial fibrillary acidic protein)
Diseases named in the same sentence as GFAP in open-access papers (continued):
Sharing a sentence is not in itself a finding about the gene and the disease.
neurological diseases (continued). "Indeed, reactive astrocytes – classically recognizable for their hypertrophic aspect and increased expression of markers such as glial fibrillary acidic protein (GFAP) (an intermediate filament marker) – have been identified in most neurological diseases." (PMID 33195262, 2020). "Further studies of this compound, and of subsequent-generation drugs that target GFAP, tubulin, and their interface, might provide even more effective therapeutic agents for the prevention or reversal of neurological disorders such as AD." (PMID 31920540, 2019). "That is, AxD, which belongs to monogenic neurological diseases, has a broader AAO than previously thought, suggesting the existence of modifier genes other than causative GFAP mutations contributing to the diversity of AAO, especially in the bulbospinal type and intermediate form." (PMID 31611638, 2019). "Future gene therapies for neurological disorders could benefit from using a GFAP promoter to regulate transgene expression in response to disease-induced astrocytic reactivity." (PMID 31754385, 2019). "Comparably little, however, is known about GFAP release in other neurological disorders." (PMID 23626774, 2013). "However, since GFAP levels may also be elevated in other neurological disorders beyond AD, further investigation into these conditions is required." (PMID 40943059, 2025). "However, there is a demand to investigate GFAP concentrations in other neurological disorders." (PMID 39594187, 2024). "However, its sensitivity may be insufficient to reliably measure GFAP in the blood, of which concentrations in most patients with neurological disorders range from 10−14 to 10−10 M (0.5–5,000 pg/mL)." (PMID 35370870, 2022). "In addition, increases in CD-68 and GFAP which are markers of microglia and astrocytes are seen in neurological diseases and may contribute to the inflammation and disease." (PMID 33396967, 2020). "Furthermore, exacerbation of GFAP or astrogliosis along with secretion of pro-inflammatory cytokines, including TNF-α, are known to be highly expressed in the central nervous system during neurologic diseases associated with inflammation." (PMID 29262526, 2017). "Interestingly, a previous study looking into the tissue expression of YKL-40 and GFAP using in situ hybridization and immunohistochemistry demonstrated a positive association between GFAP immunostaining and YKL-40 transcription in various neurological disorders." (PMID 26270969, 2015). "Therefore, the capacity of CNF1 of modulating GFAP content could result crucial in those neurological diseases where astrocytosis contributes to neuronal damage." (PMID 22523545, 2012). "Blood-based biomarkers reflecting neuronal and astroglial injury, such as neurofilament light chain (NfL) and glial fibrillary acidic protein (GFAP), have been exploited in healthy subjects and a variety of neurological disorders including TBI." (PMID 40514556, 2025). "After adjustment for age and neurological diseases, patients with GOS 1–3 outcome had significantly higher concentrations of NfL and GFAP." (PMID 38769253, 2024). "TBI-induced protein upregulation (MUG-1, PZP, GFAP, TJP, STAT-1, and CD44) across hippocampal sub-regions indicates shared molecular responses and links to neurological disorders." (PMID 38735925, 2024). "Several CSF molecules have been proposed as reliable markers for glial cell activation within CNS, potentially reflecting the involvement of astrogliosis (i.e. GFAP) and microgliosis (i.e. soluble TREM2) in the pathogenesis of neurological disorders." (PMID 38142915, 2024). "Both NfL and GFAP correlated with 10–15-year GOS 1–5 (rs = − 0.34, p = 0.026, and rs = − 0.37, p = 0.013), but after adjustment for age and neurological diseases, the correlation was lost (rs = − 0.27, p = 0.088, and rs = − 0.24, p = 0.13)." (PMID 38769253, 2024).
neurological diseases (continued). "Reactive astrogliosis is characterized by increased levels of glial fibrillary acidic protein (GFAP), release of inflammatory cytokines, and morphological changes in many neurological diseases." (PMID 37032635, 2023). "GFAP and its decomposition products are released into biological fluids rapidly after SCI, which work as a candidate biomarker for neurological disorders." (PMID 34381025, 2021). "For example, glial fibrillary acidic protein (GFAP) was previously reported in blood and its increased levels were found in patients with different neurological diseases, as a possible consequence of astroglial destruction." (PMID 30872628, 2019). "Lastly, expression of glial fibrillary acidic protein (GFAP), which is an astroglial pathology biomarker in neurological diseases, was evaluated in the medial prefrontal cortex, nucleus accumbens, and hippocampus." (PMID 28056040, 2017). "Despite promising findings, plasma GFAP is not yet validated as a reliable biomarker for AD diagnosis, as its elevation is observed in multiple neurological disorders." (PMID 40690136, 2025). "After adjustment for age and previous neurological diseases, logistic regression was performed for the outcomes GOS 1 (dead) or GOS 2–5 (alive) and GOS 1–3 (poor) or GOS 4–5 (good) versus the independent continuous variables (NfL and GFAP)." (PMID 38769253, 2024). "Moreover, increased immunoreactivities for GFAP and Iba1 and elevated levels of CXCL13 and CCL12, the chemokines involved in central leukocyte recruitment and other neurological diseases, were also observed in the brain." (PMID 36157272, 2022). "For example, levels of the brain-derived glial fibrillary acidic protein (GFAP), S100B, tau and Ubiquitin C-Terminal Hydrolase L1 (UCHL-1) in biological fluids have been shown to correlate with presence and severity of many neurological disorders." (PMID 27903281, 2016). "However, when adjusted for age and neurological disease, NfL and GFAP did not relate to mortality at 10–15 years after trauma." (PMID 38769253, 2024). "In conclusion, this study successfully demonstrated that the GFAP Chemiluminescent Enzyme Immunoassay (CLEIA) exhibited the convenience and good analytical performance necessary for GFAP measurements to aid in the differential diagnosis of neurological disorders." (PMID 39594187, 2024). "However, raised GFAP levels are not specific to AD, and are also increased in many other neurological diseases." (PMID 38623387, 2024). "On the other side, cotreatment with WSLE and WSLE NE revealed a signification downregulation of APP, GFAP, vimentin, TGF-β, Smad2, and BAX target genes which coincided with previous studies which highlighted the neuroprotective effect of WSLE in a variety of neurological disorders." (PMID 38630361, 2024). "Of note, glial activation is not specific to AD pathophysiology, elevated blood GFAP levels could be observed in other neurological diseases (e.g., FTD, VaD), as our and other studies have shown." (PMID 36750875, 2023). "SOX11 is suggested to function in the developing nervous system while lack of glial fibrillary acidic protein (GFAP) gene function in knock-out mice increases the outgrowth of axons from neurons of the spinal cord (GFAP is central in an IPA cluster related to neurological disorders." (PMID 21042590, 2010). "However, its combination with other biomarkers, such as glial fibrillary acid protein GFAP, Myelin basic protein (MBP), and interleukins, could provide disease-specific signatures to discriminate between neurological disorders in the future—a currently unmet need in the real-world clinical setting." (PMID 40309835, 2025). "However, GFAP is not specific for AD but is related to many neurological diseases." (PMID 37829140, 2023).
neurological diseases (continued). "This difference between male and female Rhes KO mice in GFAP levels did not surprise, since it was previously reported that astrocytes may participate in the generation of gender differences in the etiology of neurological disorders or in the response of the brain to pathological insults." (PMID 29904346, 2018).
cancer (119 papers, 2008 to 2026). A tumor composed of atypical neoplastic, often pleomorphic cells that invade other tissues. "The performance of GFAP varies by cancer type, yet its diagnostic utility is enhanced when combined with NfL,18 highlighting the potential of multi-biomarker models to enhance diagnostic accuracy." (PMID 40814421, 2025). "NfL and GFAP emerged as the most promising biomarkers, demonstrating moderate to strong diagnostic performance across multiple cancer types." (PMID 40814421, 2025). "These vectors carried the Cre recombinase gene controlled by a glial fibrillary acidic protein (GFAP) promoter, along with sgRNA under the control of a U6 promoter, targeting 56 genes commonly mutated in human cancers." (PMID 40007819, 2024). "ORF of Cre-recombinase under control of GFAP promoter and sequences of sgRNAs under control U6 promoter targeting genes associated with cancer." (PMID 40007819, 2024). "Cancer screening appropriate for age, sex, and risk factors is recommended for GFAP antibody-positive patients, especially for patients with atypical clinical and radiologic manifestations." (PMID 35153997, 2022). "These cells show also the typical reduction of GFAP expression, a hallmark of cancer cells associated to the overall increase in ErbB3 synthesis, as shown from qPCR analysis performed on total RNA extracted from patient biopsies." (PMID 35255831, 2022). "More recently described biomarkers are considered either intermediate risk (with 30–70% risk for cancer, such as α-amino-3-hydroxy-5-methyl-4-isoxazolepropionic [AMPA]-receptor [R] antibody) or low risk (with 30% cancer risk, such as glial fibrillary acidic protein [GFAP]-IgG) [3, 4•]." (PMID 36781586, 2023). "Our findings support this, and indicate that GFAP levels in TGCT cancer tissues could also be used as a diagnostic factor." (PMID 35454778, 2022). "In addition to the elevated expression of GFAP, some astrocytes associated with cancer cells simultaneously regulate the expression of nestin, another marker of reactive astrocytes." (PMID 31900168, 2020). "We recently showed that quantification of the relative level of GFAPδ to GFAPα, the GFAPδ/GFAPα ratio, using RNA sequencing data obtained from the cancer genome atlas (TCGA) indeed indicates that low‐ and high‐grade astrocytoma express different combinations of GFAP variants." (PMID 30667110, 2019). "In this study, we found that CCA cell-derived lactate stimulated the dedifferentiation of SCs and significantly induced HMGB1 expression in GFAP+ dSCs, enhancing malignancy of cancer cells." (PMID 40148311, 2025). "We found migration of cancer cells towards the nerve explant, reaching GFAP+ SCs coming from the nerve." (PMID 38474330, 2024). "We also found that more NEUN+ neurons than GFAP+ astrocytes in the co-cultured cerebral organoids were labelled with mCherry from sLP-mCherry-231 cancer cells." (PMID 38951862, 2024). "Immunofluorescence analysis in clinical GBM samples demonstrated that there were malignant cells with co-staining of TNFRSF14 and GFAP, indicating cancer intrinsic TNFRSF14 expression in GBM." (PMID 39085878, 2024). "As is the case with NfL, recently developed ultra‐sensitive assays allow quantification of GFAP in peripheral blood, opening up possibilities to study astrocyte injury and activation in cancer patients, both during treatment and at long‐term follow‐up." (PMID 39030984, 2024). "Biomarkers reflecting neuronal injury (neurofilament light chain protein), astrocyte injury or activation (glial fibrillary acidic protein) as well as inflammation (YKL‐40) were significantly elevated in cancer survivors compared to controls." (PMID 39030984, 2024). "The canonical isoform GFAP is downregulated in higher-grade cancers, resulting in greater GFAP isoform dominance in the network." (PMID 37509607, 2023).
cancer (continued). "Metastatic cancer cells induce astrogliosis by activating the surrounding astrocytes, marked by increased glial fibrillary acidic protein (GFAP) expression and cellular processes." (PMID 37149684, 2023). "We found that levels of GFAP promoter methylation were higher in cancer tissue than in normal tissue, and continued to increase as clinical staging progressed." (PMID 35454778, 2022). "We also found that LC3 expression was even stronger in nerves than in PanCa tissue and had the same position as GFAP staining-positive SCs, indicating that the interaction between cancer cells and nerves can promote autophagy in SCs." (PMID 35109895, 2022). "This study constructed a pGFAP-HSVtk-P2A-EGFP plasmid bearing the HSVtk/GCV system controlled by the GFAP promoter to establish a strategy for cancer management in vitro." (PMID 34370752, 2021). "Co-culture of Schwann cell with HSC-3 cancer cells also resulted in Schwann cell activation as confirmed by the overexpression of c-Jun, GFAP, p75NTR, and downregulation of MBP." (PMID 33469141, 2021). "Here, mice receiving Zfra4-10 or WWOX7-21 peptide alone exhibited an increased binding of endogenous tumor suppressor WWOX with ERK, C1qBP, NF-κB, Iba1, p21, CD133, JNK1, COX2, Oct4, and GFAP in the spleen, brain, and/or lung which led to cancer suppression." (PMID 32764489, 2020). "Using immunofluorescence analysis, the protein expression of Nestin, Sox2, Vimentin, and GFAP was analyzed in these primary cancer cell lines." (PMID 32742192, 2020). "The arrest and extravasation of cancer cells result in a strong local activation of astrocytes, detected by the upregulation of glial fibrillary acidic protein (GFAP) as well as by hyperdilation of astrocyte processes." (PMID 31900168, 2020). "Cancer-bearing rats also displayed significant increase in glial fibrillary acidic protein (GFAP) staining in the marginal nucleus, substantia gelatinosa, nucleus proprius and laminæ 7–8, as compared to sham animals." (PMID 31882872, 2019). "Serum from non-cancer healthy control individuals had very few detectable CD9+/GFAP+/SVN+ exosomes, although CD9+/GFAP+ exosomes were detectable in small numbers." (PMID 29383115, 2017). "In contrast, a small but detectable fraction (range 2.7 – 3.2%; mean = 2.9%) of CD9+ exosomes from non-cancer healthy controls had GFAP on their surface (a 7.9-fold difference)." (PMID 29383115, 2017). "These small dots were similar to those of previous reports using cancer cell line models with overexpression of GFAP (overexpression models: OE models)." (PMID 27402089, 2016). "False positives, for example genes with high expression in both normal and cancer tissues, such as GFAP, were more often identified by the other methods such as COPA, which otherwise also performed well." (PMID 21365010, 2011). "In all cases, GBM classification includes expression of the glial fibrillary acidic protein (GFAP) in cancer cells, a marker of astrocytes and NSCs." (PMID 24212782, 2011). "This notion is supported by the observation that c-Fos expression is upregulated in L3-L5, and GFAP labeling is increased in L2-L5 in animals bearing cancer in the femur." (PMID 20602757, 2010). "Also, in the presence of cancer cells, SCs upregulate the expression of glial fibrillary acidic protein (GFAP), typical of dedifferentiated SCs and involved in the nerve repair process." (PMID 39906323, 2024). "Interestingly, chains of GFAP+ activated Schwann cells (SCs) from the nerve reached out towards cancer cells." (PMID 38474330, 2024). "However, this extremely high tissue specificity also prevents GFAP from being an ideal pan-cancer classification marker, resulting in very low mean occlusion scores." (PMID 39118043, 2024).
cancer (continued). "In response to a variety of brain injuries, including BBB damage and cancer, astrocytes undergo a process of reactive gliosis that involves upregulation of the intermediate filament GFAP, as well as a number of growth factors, inflammatory cytokines, and extracellular matrix proteins." (PMID 36993983, 2023). "Indeed, in P19 carcinoma cells P2X7r activation promotes gliogenesis with the expression of the astrocytic marker GFAP." (PMID 38164435, 2023). "Finally, by sub-cloning A-VV5, we obtained a cell line (A-FC6) that still retained some astrocytic properties, including expression of the glial fibrillary acidic protein (GFAP), but hosting chromatin alterations typical of cancer cells." (PMID 33322092, 2020). "Notably, Zfra4-10 or WWOX7-21 peptide induced the binding of endogenous WWOX with ERK, C1qBP, NF-κB, Iba1, p21, CD133, JNK1, COX2, Oct4, and GFAP in the spleen, brain, and/or lung, which correlates with cancer suppression." (PMID 32764489, 2020). "Immunofluorescence analysis demonstrated the presence of de-differentiated NESTIN+ and SOX2+ cancer cell populations as well as oligodendrocytes (O4), astrocytes (GFAP) and neurons (TUJ-1) confirming the in vivo differentiation potential of the generated GTIC-like cells." (PMID 26899176, 2016). "Cells exhibiting high expression of BCAN, GFAP, and EGFR were categorized as cancer cells, while endothelial cells displayed elevated levels of FLT1, CLDN5, and ABCG2." (PMID 41041071, 2025). "Because microglial activation is often accompanied by astrogliosis during cancer therapies, we tested the effect of combi-ICI on glial interplay by determining the volume of GFAP immunoreactivity (astrocytes) in the DG." (PMID 40313772, 2025). "CCS showed elevated GFAP, MCP-1, and Total Tau compared to HCs, suggesting persistent neuroimmune alterations, possibly reflecting the long-term biological impact of cancer and its treatment." (PMID 40838185, 2025). "Immunohistochemically, MAME tumors exhibit features similar to basal-like carcinomas, with expression of CK5/6, CK14, SMA, P63, S100, cadherin, GFAP, and other markers." (PMID 39882520, 2024). "For instance, GFAP expression levels are correlated with clinical outcomes and the cell fate regulation of GBM cancer stem cells (CSCs), as well as GBM-CSC invasion." (PMID 37886397, 2023). "We used flow cytometry to quantify different cell types in cultures, including neural, stem/progenitor cells (Nestin), cancer stem cells (CD133) neuronal (TUJ1), glial (GFAP), and the proliferative population (Ki67)." (PMID 37508868, 2023). "For comparative reasons only, positive likelihood ratios for widely used clinically established cancer screening tests are far less than those for the TBI biomarkers in the given study, except for GFAP." (PMID 34827575, 2021). "CAR significantly decreased the mRNA expression of stem cell markers and increased the expression of the GFAP mRNA, thus demonstrating its ability to modulate the de-differentiation of GBM cancer cells." (PMID 29123181, 2017). "We also report H&E staining and immunohistochemistry for HLA-A, CD45, Ki67, GFAP, and CEA protein expression between patient cancer tissues and PDX models." (PMID 29296105, 2017). "Factors upregulated in the cancer pain state, such as IL-1β, PPD mRNA, dynorphin, GFAP, and substance P were decreased after electroacupuncture treatment." (PMID 25383081, 2014). "Gene expressions in GFAP+ cells, composed mainly of cancer cells, were not significantly changed after SoC therapies." (PMID 39423857, 2025).